LRP1 (LDL receptor related protein 1)
Diseases named in the same sentence as LRP1 in open-access papers (continued):
Sharing a sentence is not in itself a finding about the gene and the disease.
glioma (continued). "We therefore analyzed the regional distribution of CXCR3 and LRP1 by focusing on high-grade gliomas (glioblastomas, GBM)." (PMID 29146996, 2017). "We were able to detect that PAI-1 indeed binds to LRP1 in human glioma tissue attributing, to a certain extent, these interactions with LRP1 on MCs." (PMID 26164207, 2015). "Similar staining was performed on human glioma tissue demonstrating the LRP1 expression on MCs in vivo." (PMID 26164207, 2015). "Considering that LRP1 is expressed on other cell types in glioma in addition to MCs, we wanted to ascertain in vivo interaction of LRP1 and PAI-1in MCs." (PMID 26164207, 2015). "We are first to identify the LRP1 expression in MCs in both LAD2 cells and human gliomas and show that LRP1 was critical for accumulation of MCs towards PAI-1 expressing glioma cells." (PMID 26164207, 2015). "Second, LRP1 protein levels were dramatically higher in brain tissue from mice carrying orthotopic glioma tumours than normal mice." (PMID 22027709, 2011). "Gliomas are particularly aggressive tumours, and it was therefore of interest to examine how expression of LRP1 and the transport of Angiopep-2 conjugates were affected by conditions associated with cancer microenvironment, such as hypoxia and low pH." (PMID 22027709, 2011). "To examine this model, we started by quantifying the expression levels of LRP1 protein in animals bearing glioma tumours by western blot analysis." (PMID 22027709, 2011). "Moreover, activation of the PAI-1/LRP1 axis, involved in mast cell recruitment in gliomas, enhances STAT3 phosphorylation and exocytosis." (PMID 40002669, 2025). "Moreover, glioma cells as well as endothelial cells of the BBB express high amounts of low-density lipoprotein receptor-related protein-1 (LRP1), which mediates the transcytosis of multiple ligands across the BBB (such as lactoferrin, melanin, transferrin)." (PMID 39194524, 2024). "As such, LRP1 might represent a promising target in the CNS, but will require more preclinical studies to decipher its role in glioma cancer cell clearance." (PMID 38786045, 2024). "Hence, the utilization of LRP1-mediated transcytosis presents a potential strategy for targeted delivery of glioma medication to the specific affected region by traversing the BBB." (PMID 38087359, 2023). "Herein, nanoprobes were caged with four-armed oligomers and subsequently modified with a novel DBCO–PEG-modified retro-enantio peptide ligand reL57, enhancing cellular uptake into U87MG glioma cells highly expressing low-density lipoprotein receptor-related protein 1 (LRP1)." (PMID 37896282, 2023). "Appending Angiopep-2 to LNPs may be favorable as it can promote transport across the BBB and shows specificity for glioma cells that overexpress low-density lipoprotein receptor-related protein-1 (LRP1) on their surfaces." (PMID 36012619, 2022). "We hypothesize that low MT1-MMP-to-LRP-1 ratios or MT1-MMP inhibition would ultimately favor LRP-1-mediated internalization of An2–drug conjugates in gliomas." (PMID 36430705, 2022). "LRP1 is widely expressed in human and mouse BCECs and gliomas, making angiopep-2 an attractive targeting moiety for various nanoparticles for brain delivery and glioma targeting." (PMID 35336049, 2022). "Interestingly, the present study, for the first time, demonstrated a significant positive correlation of LRP-1 with ABCA-1 in glioma tumor samples as well as in the external data sets." (PMID 36267880, 2022). "Importantly, inhibiting endocytosis by targeting DNM2 or LRP-1 protects glioma cells against gefitinib treatment during cell dissemination from tumour spheroids." (PMID 34831480, 2021). "Importantly, we showed that inhibition of DNM2 or LRP-1 also decreased glioma cell responsiveness to gefitinib during cell evasion from tumour spheroids." (PMID 34831480, 2021). "In addition, LRP1 depletion or functional silencing further increased cell migration of glioma cells." (PMID 29146996, 2017).
glioma (continued). "More importantly, LRP-1 is also over-expressed in human glioma cells." (PMID 27765902, 2016). "Proximity ligation assay (PLA) was used to detect binding of PAI-1 with LRP1 in glioma tissue." (PMID 26164207, 2015). "We hypothesized that LRP1 is expressed on MCs and mediates MC motility towards glioma derived PAI-1." (PMID 26164207, 2015). "The glioma transplants correlated with high expression levels of LRP1." (PMID 22027709, 2011). "Low-density lipoprotein receptor-related protein 1 (LRP1) is a large single-pass transmembrane receptor that is highly expressed in brain endothelial cells and upregulated in some effector cells, such as melanized neurons in the substantia nigra and glioma cells." (PMID 37896282, 2023). "Finally, delivery of the Thera-cHANPs is reached by using angiopep-2 able to trigger transcytosis and traverse the BBB by recognizing low-density lipoprotein related protein-1 (LRP-1) expressed on the brain capillary endothelial cells and overexpressed on glioma cells." (PMID 33525655, 2021). "Intracranial glioma accumulation of SP-sLip may be at least partially attributed to LRP1 mediation." (PMID 31395892, 2019). "Besides on the BBB, LRP1 was also found to be highly expressed on glioma cells." (PMID 31395892, 2019). "Consistent with its relatively high expression in glioma cells, LRP1 protein levels in total brain tissue were significantly higher in mice carrying glioma tumours than normal animals, demonstrating that the presence of glioma transplants correlated with increased expression of LRP1." (PMID 22027709, 2011). "These innovative nanocarriers have demonstrated the ability to transport paclitaxel (PTX) through the BBB, facilitated by the low-density lipoprotein receptor-related protein 1 (LRP1), thus showing great potential for treating gliomas." (PMID 39735671, 2025). "LRP1 (low-density lipoprotein receptor-related protein 1), a receptor protein that is abundant on the surface of both BBB and glioma cells, is planned to transport Paclitaxel (PTX) across the BBB using Nanoparticles." (PMID 39735671, 2025). "Low-density lipoprotein receptor-related protein 1 (LRP-1) is overexpressed on the BBB and glioma cells, providing a promising target for radiosensitizers." (PMID 39766452, 2024). "Due to its dual conjugation, DOX-TAT-Ang-LIP was not only transcytosed via LRP1 across the BBB, but also entered glioma cells TAT dependently for their subsequent necrosis due to the release of doxorubicin." (PMID 39289695, 2024). "This ligand targets the low-density lipoprotein receptor-related protein-1 (LRP1), which is overexpressed in the BBB and glioma cells." (PMID 38931430, 2024). "Targeting low-density lipoprotein-receptor-related protein 1 (LRP1) recently gained interest because of its high expression in both the BBB and glioma." (PMID 36765816, 2023). "The angiopep-2 peptide that binds to low-density lipoprotein receptor-related protein-1 (LRP-1) was conjugated to paclitaxel via a succinyl group (named ANG1005) and applied to the treatment of glioma and metastatic breast cancer." (PMID 37258584, 2023). "PAI-1 binds to the low-density lipoprotein receptor-related protein 1 (LRP1) receptor, activating intracellular signalling cascades and modulating cell migration, such as mast cells in gliomas." (PMID 37958602, 2023). "Low-density lipoprotein receptor protein 1 (LRP1) is highly expressed on brain capillary endothelial and glioma cells, and angiopep-2 (ANG) is a type of peptide with a high affinity for LRP1." (PMID 37481646, 2023). "The expression of LRP1, the specific ligand for ANGIOPEP-2, was the highest in C6 cells among five studied glioma cell lines." (PMID 36145687, 2022). "LRP-1 was significantly upregulated in the U87MG and LN229 glioma cell line at mRNA and protein levels than in the normal brain." (PMID 36267880, 2022).
glioma (continued). "Low density lipoprotein receptor related protein-1 (LRP-1) is highly expressed on BBB and overexpressed on glioma cells and, for this reason, constitutes a fascinating option for dual targeting purposes." (PMID 33525655, 2021). "Our results highlight for the first time the instrumental role of LRP-1 in gefitinib-mediated EGFR internalisation and glioma cell dissemination." (PMID 34831480, 2021). "The low-density lipoprotein receptor related protein 1 (LRP1) is highly expressed in the endothelial cells of the brain capillary and the glioma cells." (PMID 31617104, 2019). "Our study demonstrated the expression of LRP1 in human MC line LAD2 and in MCs in human high-grade glioma." (PMID 26164207, 2015). "For these studies, we chose glioblastoma U87 as a model system, which expresses LRP1 in abundance in vitro, and examined the brain biodistribution pattern of ANG1005 and Angiopep-2 bearing human glioma xenografts." (PMID 22027709, 2011). "Lactoferrin is a glycoprotein (possessing two transferrin families) that could be specifically bound by low-density lipoprotein receptor-related protein 1 (LRP-1), which is highly expressed on BBB endothelial cells and glioma cells." (PMID 39996667, 2025). "A PDGFB::LRP1 has not yet been reported in ependymomas or subependymomas, but only in one low-grade glioma without a definite histological diagnosis." (PMID 38581034, 2024). "Angiopep-2 (TFFYGGSRGKRNNFKTEEY) targets low-density lipoprotein receptor-related protein 1 (LRP-1) that is overexpressed by both endothelial cells of the BBB and glioma cells and has been used to coat hyaluronic acid NPs to enhance delivery to human glioblastoma cells." (PMID 38794182, 2024). "Low‐density lipoprotein receptor‐related protein‐1 (LRP1) mediates multiple ligands across the BBB and is abundantly expressed in gliomas, while Angiopep‐2 (Ang) is a targeting peptide with a high affinity for LRP1 and trans‐activator of transcription (TAT) is an efficient cell‐penetrating peptide." (PMID 37080941, 2023). "Others were robust and shared across most samples such as CD74 receptor binding to MIF, COPA, or APP as cognate ligands and SPP1-CD44 (myeloid to glioma signaling) and TNFRSF1A-GRN, PGRMC2-CCL4L2, MDK-SORL1 or LRP1, and GPR37L1-PSAP (glioma to myeloid signaling)." (PMID 35140215, 2022). "Overall, molecular docking results allowed us to define the molecular pattern at the basis of the ANG-2/LRP-1 interaction, responsible for the transcytosis at the endothelial layer of the BBB and boosted uptake by glioma cells, as already proved by different authors." (PMID 36235232, 2022). "Importantly, this peptide exploits the low density lipoprotein receptor related protein-1 (LRP-1)—expressed both by brain microcapillary endothelial cells and by glioma—to gain access to the brain parenchyma via receptor-mediated transcytosis." (PMID 33562146, 2021). "In addition, low-density lipoprotein receptor-related protein 1 (LRP1) was found to be highly expressed in BBB and glioma cells too." (PMID 34209892, 2021). "In vitro studies were performed with two different cell lines: C6 glioma cells, with high expression of low density lipoprotein receptor-related protein 1 (LRP1), a known receptor of Lf; and ECV 304 cells with no LRP1 expression." (PMID 30674838, 2018). "This indicates that LRP-1 is a potential target moiety for drug delivery systems, as it could be used for targeting not only the BBB but also glioma." (PMID 27765902, 2016). "Also, active crossing and targeting are achieved by theranostic cHANPs decorated with angiopep-2 (Thera-ANG-cHANPs), a dual-targeting peptide interacting with low density lipoprotein receptor related protein-1(LRP-1) receptors overexpressed by both endothelial cells of the BBB and glioma cells." (PMID 33525655, 2021).
glioma (continued). "Moreover, the overexpression of LRP-1 has also been detected in glioma cells, indicating that targeting LRP-1 may be a potential treatment option for glioma targeted drug delivery." (PMID 32474457, 2020). "Furthermore, to address the potential implication of low-density lipoprotein receptor-related protein 1 (LRP1) in this process, we demonstrated the expression of LRP1 in LAD2 cells but also revealed the presence of LRP1 in MCs in human high-grade glioma tissue." (PMID 26164207, 2015). "In vitro studies involved two cell lines: C6 glioma cells, expressing high levels of low-density lipoprotein receptor-related protein 1 (LRP1), a known Lf receptor; and ECV 304 cells with no LRP1 expression." (PMID 39905470, 2025). "LRP1, the other receptor of CALR on phagocytes, has not been studied in gliomas." (PMID 38786045, 2024). "Despite the growing interest of the scientific community in understanding LRP-1 functionalities in tumour progression and resistance to treatments, the role of LRP-1 in the regulation of EGFR trafficking and glioma cell resistance to TKI had never been addressed so far." (PMID 34831480, 2021).
breast carcinoma (45 papers, 2010 to 2025). "Consistently, C766T LRP1 gene polymorphism, which has been previously associated with neurodegenerative disease, also correlates with increased breast cancer occurrence." (PMID 29108253, 2017). "Through a series of elegant experiments, the researchers demonstrated that PCSK9 promotes metastasis by downregulating LRP1 on the surface of breast cancer cells." (PMID 39872986, 2025). "The somatic mutation patterns of ERGs in breast cancer highlighted APOB, LRP1, and VPS13B as the top 3 frequently mutated genes." (PMID 39792732, 2025). "High gene expression of TNFRSF9, HOMER1, and LRP1 were all significantly correlated with worse relapse free survival in breast cancer." (PMID 39483900, 2024). "According to simulation results, the remaining ten amino acid sequences (CSRLSLPGSS) that we call SRL-2 in this study displayed a significant affinity for the low-density lipoprotein receptor-related protein (LRP-1) in breast cancer." (PMID 38084295, 2023). "A higher LRP-1 expression has also been reported in MDA-MB-231 breast cancer cells and HCT-15 colorectal cancer cells and can be related to the pro-tumoral effect of LRP-1 in some types of cancer cells." (PMID 37768946, 2023). "Recent studies have shown that the low-density lipoprotein receptor-related protein 1 (LRP-1) receptor has a significant impact on the development of breast cancer." (PMID 38084295, 2023). "Previous work showed that LRP-1 promoted invasion, survival or metastatic dissemination of thyroid carcinoma and breast cancer cells." (PMID 37768946, 2023). "A recent publication demonstrated that LRP1 mediates Notch pathway activation, and knocking out LRP1 attenuates Notch-signaling-dependent invasion, migration and tumorigenesis of leukemia and breast cancer cells." (PMID 37020553, 2023). "In conclusion, our meta-analysis of the literature suggests that incorporating chimeric peptides, specifically designed to interact with the LRP-1, holds promise as a targeted approach for drug delivery in breast cancer treatment." (PMID 38084295, 2023). "In this study, we identified that CD44s-tPA axis enhanced lamellipodia formation process via activating LRP1-NFκB signaling pathway in luminal type breast cancer (BrCa)." (PMID 37842093, 2023). "Previous studies reported that high LRP1 expression was related to tumor cell migration, invasion, or poor prognosis, such as in breast cancer, glioblastoma, and pancreatic ductal adenocarcinoma." (PMID 35628341, 2022). "In breast cancer cell lines, serpinE2 can bind to LRP1 on the cell membrane and activate the ERK1/2 signaling pathway." (PMID 36439874, 2022). "Recently, MT1-MMP has been shown to shed LRP1 in breast carcinoma MCF7 cells as well as in vascular smooth muscle cells and in cartilage." (PMID 33767172, 2021). "In breast cancer, early reports indicated that a low expression of LRP1 correlated with more aggressive tumors." (PMID 32655497, 2020). "Previous work has reported LRP-1 as supporting invasion, survival or metastatic dissemination of thyroid carcinoma and breast cancer cells." (PMID 29108253, 2017). "The aspartic protease cathepsin-D, whose overexpression is correlated with poor prognosis in breast cancer, is also endocytosed by LRP-1." (PMID 29108253, 2017). "For example, several reports have shown that low expression of LRP1 is closely related to the aggressive phenotype of tumor cells derived from various tissues, such as human prostate, thyroid, and breast cancer." (PMID 22427881, 2012). "The results suggest that our cleavable stealth chimera peptide (SRL-2) could potentially serve as a targeted therapy for breast cancer by selectively binding to LRP-1 in the TME and evading immune detection due to its antifouling properties." (PMID 38084295, 2023).